CRIPTO (cripto, EGF-CFC family member)
Diseases named in the same sentence as CRIPTO in open-access papers (continued):
Sharing a sentence is not in itself a finding about the gene and the disease.
Azoospermia (1 paper, 2020). Absence of any measurable level of sperm,whereby spermatozoa cannot be observed even after centrifugation of the semen pellet. "The reason for detection of CRIPTO in the epididymal obstructive azoospermia cases is still elusive, but we hypothesize it might be due to incomplete obstruction allowing passage of the cleaved CRIPTO protein despite no passage of sperm cells." (PMID 32210110, 2020). "Despite the absence of spermatozoa, CRIPTO was detected at levels similar to controls for non-obstructive azoospermia with JS ≥ 4, and at higher average levels for non-obstructive azoospermia with JS < 4 (not statically significant)." (PMID 32210110, 2020). "Yet, in this instance, it is important to note that this correlation existed within the control group, which had an overall lower average CRIPTO concentrations than the non-obstructive azoospermia and TGCT sample groups." (PMID 32210110, 2020). "In the non-obstructive azoospermia samples, we also found the highest average miR-371a-3p reading in the group with the lower Johnsen’s score; we hypothesize this may be due to a cell-type dilution effect for CRIPTO." (PMID 32210110, 2020). "Our assay detected CRIPTO both in non-obstructive azoospermia (62/67, 92.5%) and in epididymal obstructive azoospermia (10/10, 100%), but was negative in the single structural obstruction (CBAVD) sample with enough material for CRIPTO assessment." (PMID 32210110, 2020).
Cirrhosis (1 paper, 2021). A chronic disorder of the liver in which liver tissue becomes scarred and is partially replaced by regenerative nodules and fibrotic tissue resulting in loss of liver function. "Altogether, these results indicated that livers of patients with cirrhosis express higher levels of CRIPTO compared to control liver tissue and that the level of CRIPTO staining is correlated to the MELD score." (PMID 34943832, 2021). "Circulating CRIPTO levels were measured in plasma samples of patients with cirrhosis registered at the waitlist for liver transplantation (LT) and 1 year after LT." (PMID 34943832, 2021). "The observed correlation of CRIPTO expression with disease stage suggests a functional role for CRIPTO in the fibrosis-cirrhosis-HCC cascade, rendering it as a potential and interesting marker for disease monitoring or even as a novel treatment target." (PMID 34943832, 2021). "A significant decrease in plasma CRIPTO concentration was also observed when the ALD and viral-induced cirrhosis cohorts were analyzed separately." (PMID 34943832, 2021).
End Stage Liver Disease (1 paper, 2021). Final stage of a liver disease when the liver failure is irreversible and LIVER TRANSPLANTATION is needed. "The expression of CRIPTO in the liver was found specifically in the hepatocytes and was positively correlated with the Model for End-stage Liver Disease (MELD) score for end-stage liver disease." (PMID 34943832, 2021). "The levels of CRIPTO expression in the hepatocytes of HCC patients positively correlated with the MELD scoring system for end-stage liver diseases, illustrating that CRIPTO expression is related to the severity of the disease." (PMID 34943832, 2021). "In addition, we observed elevated CRIPTO levels in most (69%) of the measured plasma samples of patients with end-stage liver disease, which decreased after the patients underwent LT." (PMID 34943832, 2021).
gastric cancer (1 paper, 2021). A primary or metastatic malignant neoplasm involving the stomach. "Together with downregulated E-cadherin (found in 70% of cases), upregulated CRIPTO was found in 54% of gastric cancer cases, and this was associated with lymph node metastasis, liver metastasis and late TNM stage." (PMID 34576327, 2021). "Additionally, in gastric cancer a positive association between CRIPTO and STAT3 was reported." (PMID 34576327, 2021). "Furthermore, high CRIPTO expression in non-small cell lung cancer (NSCLC), as well as in gastric cancer, has been shown to be a predictor of poor prognosis." (PMID 34576327, 2021).
Infertility (1 paper, 2020). "In this work, we assessed the value of CRIPTO as a serum diagnostic and prognostic biomarker of TGCTs, expanding our previous series, and assessed the sensitivity of detection in seminal plasma samples of patients with both TGCTs and infertility." (PMID 32210110, 2020). "In this work, we aimed to explore the expression of CRIPTO in liquid biopsy samples of patients with TGCTs and of infertile males, extending our previous work and providing novel insight on the role of this pathway in regulating this balance between tumor development and infertility." (PMID 32210110, 2020).
leiomyosarcoma (1 paper, 2012). An uncommon, aggressive malignant smooth muscle neoplasm, usually occurring in post-menopausal women. "In addition to loss of function alterations, overexpression of teratocarcinoma-derived growth factor 1, also known as CRIPTO, results in leiomyosarcomas by deregulation of the WNT pathway." (PMID 23036318, 2012).
liver fibrosis (1 paper, 2021). "CRIPTO has a profibrotic role in both heart and liver fibrosis, and we showed for the first time that CRIPTO reactivation is linked to tissue homeostasis, wound-healing response, and fibrosis and is conserved in different tissues with low and high regenerative capacity." (PMID 34943832, 2021). "To further study the potential role of CRIPTO in liver fibrosis, we evaluated CRIPTO expression in a CCl4-induced mouse model for chronic liver fibrosis (11-week induction)." (PMID 34943832, 2021). "In the chronic and acute mouse models of liver fibrosis, CRIPTO-positive cells were observed in damaged liver areas around the central vein, which preceded the expression of αSMA-positive stellate cells, i.e., mediators of fibrosis." (PMID 34943832, 2021). "Additionally, in acute and chronic mouse models of liver fibrosis, we observed upregulation of CRIPTO that was indicative of a general and well-preserved role of CRIPTO during fibrogenesis." (PMID 34943832, 2021).
mammary adenocarcinomas (1 paper, 2021). "However, CRIPTO overexpressing mice are slow to develop mammary adenocarcinomas, and do so at a low penetrance, suggesting that while CRIPTO promotes hyperplastic growth, additional factors or cellular cues are required for progression to frank neoplastic lesions." (PMID 34576327, 2021).
metastatic tumor (1 paper, 2021). "CRIPTO expression in colonic CSCs appears to be a necessary driver for both primary tumor growth and metastatic disease in a colorectal murine xenograft model." (PMID 34576327, 2021). "CRIPTO is necessary for tumor progression and metastatic disease in multiple preclinical models." (PMID 34576327, 2021). "In humans, CRIPTO expression in NSCLC correlates with poor prognosis and increased metastatic disease." (PMID 34576327, 2021).
pancreatic cancer (1 paper, 2021). "Supporting this idea, activated MFBs/stellate cells in pancreatic cancer can induce fibrosis following chronic inflammation and have been reported to influence pancreatic CSCs in trans by secreting CRIPTO and NODAL." (PMID 34576327, 2021). "In pancreatic cancer a multicellular mechanism involving activated MFBs/stellate cells has been reported, whereby stellate cells influence pancreatic CSCs in trans by secreting CRIPTO and Nodal, and potentially thereby promoting drug resistance." (PMID 34576327, 2021).
squamous cell carcinoma (1 paper, 2022). A carcinoma arising from squamous epithelial cells. "We identified the embryonic protein CRIPTO in stem cell-enriched spheroid cultures of adenocarcinoma (AC) and squamous cell carcinoma (SCC) derived from NSCLC surgical specimens." (PMID 35719935, 2022). "Here, we show that CRIPTO is dynamically expressed in NSCLC spheroid cultures derived from surgical specimens of lung adenocarcinoma (AC) and squamous cell carcinoma (SCC)." (PMID 35719935, 2022).
cancer (23 papers, 2008 to 2025). A tumor composed of atypical neoplastic, often pleomorphic cells that invade other tissues. "Altogether, these findings indicate CRIPTO as a marker of lung CSCs possibly implicated in cancer cell plasticity and post-chemotherapy tumor progression." (PMID 35719935, 2022). "More strikingly, most literature on CRIPTO pointed to its role as an oncofetal protein associated with increased cancer features and the worst patient prognosis." (PMID 35954365, 2022). "It will be important to determine if one reason CRIPTO often involved but seldom mutated in cancer is a requirement for this kind of dynamic regulation during various stages of cancer progression." (PMID 34576327, 2021). "In the adult, CRIPTO is detected at very low levels in normal tissues and in the blood, while its increase in both tissues and blood is associated to pathological conditions, mainly cancer." (PMID 25629528, 2015). "This is very concerning, as it was reported that GRP78 and CRIPTO overexpression in the cancer cells activate MAPK/AKT signaling, Src/PI3K/AKT, and Smad2/3 pathways leading to tumor proliferation, plasticity, and resistance to apoptosis." (PMID 40360533, 2025). "This is mainly explained by overexpression of CRIPTO in these cells (also referred to as CR-1 or TDGF1), an embryonic factor associated with metastatic potential, cancer stem cell maintenance, and EMP." (PMID 40427042, 2025). "Cripto-1 (CRIPTO) was found to form a complex with csGRP78 in various types of cancers such as embryonal carcinoma, prostate cancer, and liver cancer." (PMID 40360533, 2025). "The role of CRIPTO signaling in tumor initiation and progression of tumors has been the subject of extensive exploration across various types of cancers." (PMID 39592836, 2025). "As regards GBM, despite the first evidence of a role of CRIPTO in this type of cancer, its significance in GBM progression and pathogenesis has not been addressed so far." (PMID 35954365, 2022). "Despite a large set of literature describing CRIPTO overexpression in a variety of tumors, the role of CRIPTO in cancer is less defined." (PMID 35719935, 2022). "In many of these, CRIPTO expression has been mainly detected in cancer stem cells (CSCs), suggesting its role in CSC compartment regulation." (PMID 35954365, 2022). "CRIPTO expression has been detected by our group and others on cancer stem cells (CSCs) of colorectal, hepatocellular, esophageal carcinomas and embryonal carcinoma." (PMID 35719935, 2022). "CRIPTO is an obligate co-receptor for the TGF-β family members Nodal and GDF1/3 implicated in development, pluripotency and cancer." (PMID 35719935, 2022). "CRIPTO’s ability to propagate stem cell-like phenotypes and its association (along with GRP78) in marking and regulating stem cell function implicate cancer stem cell activity in its tumor promoting effects." (PMID 34576327, 2021). "We also consider critical gaps in knowledge and resources that stand between the recent, exciting momentum in the CRIPTO field and highly actionable CRIPTO manipulation for cancer therapy and beyond." (PMID 34576327, 2021). "Although EMT and CSC identities are likely only partly overlapping, promotion of EMT is a well-established CRIPTO signaling output that almost certainly contributes to cancer promotion by CRIPTO." (PMID 34576327, 2021). "Alternatively, these zones are likely starved for other nutrients and, in this regard, we found that nutrient deprivation in vitro (i.e., serum withdrawal or glycolytic blockade) confers cancer cell CRIPTO dependency." (PMID 34576327, 2021). "The ability to differentiate healthy vs. cancer patients by serum CRIPTO levels alone indicates CRIPTO’s significant potential as a relatively non-invasive blood-based biomarker." (PMID 34576327, 2021). "In a non-carcinoma setting, serum CRIPTO levels were also higher in cirrhosis and chronic hepatitis than in volunteer control samples." (PMID 34576327, 2021).
cancer (continued). "CRIPTO has also been reported as a functional cancer stem cell marker in head and neck cancers and, more recently, in esophageal squamous cell carcinoma, hepatocellular carcinoma, and post-therapy, recurrent osteotropic prostate cancer." (PMID 33187540, 2020). "We conclude that TNBCs, and possibly many other types of cancers, critically rely on stress adaptive programs involving the CRIPTO/GRP78 signaling axis and that these can be inhibited by ALK4L75A-Fc." (PMID 33187540, 2020). "We characterized the proliferation and migration of these cells in vitro using time-lapse microscopy and characterized stress-dependent changes in the levels and distribution of CRIPTO signaling mediators and cancer stem cell markers." (PMID 33187540, 2020). "Elucidation of mechanisms governing tumor cell adaptation to stress has led to the identification of therapeutic targets such as CRIPTO for inhibiting plasticity and the emergence of subpopulations of cancer cells with facultative stem cell-like properties." (PMID 33187540, 2020). "CRIPTO-1 (CR-1) is involved in the pathogenesis and progression of human carcinoma of different histological origin." (PMID 21863025, 2011). "High CRIPTO expression levels, instead, have been related to tumorigenesis and poor prognosis in an increasing number of cancers, as for example, melanoma, breast, lung, esophageal, gastric, colon, hepatocellular, pancreatic, renal, prostate, and bladder carcinomas." (PMID 35954365, 2022). "Noteworthy, CRIPTO might be an EV marker present on the surface of vesicles released by different types of cancer cells." (PMID 35954365, 2022). "Thus, the analysis of CRIPTO expression on cell populations purged of dead cells and debris shows that CRIPTO expression is strongly increased in surviving cancer cells that are responsible for post-chemotherapy culture recovery." (PMID 35719935, 2022). "In such contexts, the emerging roles for CRIPTO in fibrotic wound healing may explain another reason for its reemergence in cancer." (PMID 34576327, 2021). "This review highlights the small signaling protein CRIPTO encoded by the tumor derived growth factor 1 (TDGF1/Tdgf1) gene, an oft cited oncofetal protein whose presence in the cancer literature as a tumor promoter, diagnostic marker and viable therapeutic target continues to grow." (PMID 34576327, 2021). "In cancers, CRIPTO expression may reflect aberrant developmental signaling associated with the stem cell promoting and differentiation inhibiting transcription factors." (PMID 34576327, 2021). "Furthermore, most analysis of human cancers has obviously focused on established lesions, and consequently, the degree to which CRIPTO marks and contributes to pre-neoplastic states that lead to cancer, remains to be determined." (PMID 34576327, 2021). "All together these data indicate that CRIPTO represents both a promising biomarker and a valid target for therapeutic intervention in cancer and that blood CRIPTO levels in humans may have clinical significance." (PMID 25629528, 2015). "The founding member of this protein family, CRIPTO, is overexpressed in various human carcinomas." (PMID 25596738, 2015). "CRIPTO-1 signaling within tumor cells has previously been demonstrated to modulate cellular growth, survival, and invasion in several human cancers, and this could be especially relevant to the biology of trophoblast cells." (PMID 25165718, 2014). "We predicted the binding site in the CRIPTO CFC domain responsible for the interaction with specific residues of GRP78 SBDβ which can be targeted both by inhibitors in future work to prevent this interaction leading to stopping the pathway responsible for cancer resistance to chemotherapy." (PMID 40360533, 2025). "Indeed, several studies support a correlation between CRIPTO levels and worse prognosis in multiple cancers, but the mechanistic role of CRIPTO in cancer cell regulation is largely unknown." (PMID 35719935, 2022).
cancer (continued). "Given this nexus, CRIPTO likely orchestrates a delicate balance between these complex signaling programs and cellular stresses, responding to contextual cues to regulate embryo-critical cellular phenotypes that can also be hijacked by cancer cells to promote tumor progression." (PMID 34576327, 2021). "And detection of CRIPTO levels may have utility as a predictive and/or prognostic marker for tumor status, for instance by assessing the serum levels of shed CRIPTO in various types of cancer." (PMID 34576327, 2021). "In humans, CRIPTO is expressed at very low levels in both normal tissues and plasma, while its expression was found increased in patients with cancer (also in both tumor tissues and plasma), suggesting that CRIPTO blood levels might have a great clinical relevance." (PMID 25629528, 2015). "In this regard, we examine CRIPTO’s restriction to rare cells in the adult, its potential for paracrine crosstalk, and its emerging role in inflammation and tissue regeneration—roles it may reprise in tumorigenesis, acting on subsets of tumor cells to foster cancer initiation and progression." (PMID 34576327, 2021). "Embryonal carcinoma-derived NCCIT cells provide a model tumor cell system to test CRIPTO inhibitors as these cells have stem cell properties and express high levels of CRIPTO protein." (PMID 33187540, 2020). "Although CRIPTO expressed from the TDGF1 gene is predominant in ESCs and germ cell tumors, a highly homologous pseudogene, TDGF1P3, is expressed and likely produces functional protein (CRIPTO-3; CR-3; TDGF3) in various cancer types, including colon, breast and lung." (PMID 34576327, 2021). "It is clear that a much larger dataset of controls, TGCT, and GCNIS-only samples is needed in order to confirm whether or not CRIPTO would be a useful cancer biomarker in this fluid, as we have suggested for blood sera." (PMID 32210110, 2020).